PLVAP (plasmalemma vesicle associated protein)
Diseases named in the same sentence as PLVAP in open-access papers (continued):
Sharing a sentence is not in itself a finding about the gene and the disease.
pancreatic adenocarcinoma (2 papers, 2021 to 2023). "PLVAP is upregulated in ECs of well-vascularized tumors, which has been associated with increased tumor angiogenesis, whereas its downregulation prevented the development of pancreatic adenocarcinoma in xenografts." (PMID 33671551, 2021).
Protein-losing enteropathy (2 papers, 2023). Abnormal loss of protein from the digestive tract related to excessive leakage of plasma proteins into the lumen of the gastrointestinal tract. "PV-1 is an essential regulator of endothelial homeostasis and permeability; as a confirmation of this important role, PLVAP gene mutations are associated with a severe protein-losing enteropathy in vivo." (PMID 36674986, 2023). "As result, the patients suffered from similar phenotypes as observed in the PLVAP-knockout mice; severe protein-losing enteropathy, characterized by excessive loss of plasma proteins in the gastrointestinal tract, a severe pathological condition that can eventually lead to death." (PMID 36781482, 2023).
retinal diseases (2 papers, 2021 to 2022). "A major component of these diaphragms is plasmalemma vesicle-associated protein (PLVAP), which has been implicated in the loss of barrier integrity in several retinal diseases such as DR and ROP." (PMID 34769308, 2021).
Salmonella Infections (2 papers, 2024 to 2025). Infections with bacteria of the genus SALMONELLA. "Furthermore, the MPF maintained the gut vascular barrier (GVB) integrity by preventing the upregulation of plasmalemma vesicle-associated protein-1 (PV1), typically induced by Salmonella infection." (PMID 40785788, 2025).
age-related macular degeneration (1 paper, 2018). Age-related loss of vision in the central portion of the retina (macula), secondary to retinal degeneration. "Interestingly, PLVAP has been shown to modulate angiogenesis as well, which indicates that PLVAP is also a target for conditions associated with angiogenesis such as age-related macular degeneration, proliferative diabetic retinopathy and cancer." (PMID 30231925, 2018).
Alzheimer disease (1 paper, 2024). A progressive, neurodegenerative disease characterized by loss of function and death of nerve cells in several areas of the brain leading to loss of cognitive function such as memory and language. "Endothelial specific inactivation of β-catenin in vivo BBB has been reported to cause significant downregulation of CLDN3, upregulation of plasmalemma vesicle-associated protein, and BBB breakdown, which leads to cognitive disorders, including Alzheimer’s disease (AD)." (PMID 38584257, 2024).
atherosclerosis (1 paper, 2025). A disease characterized by the build-up of fatty material and calcium deposition in the arterial wall resulting in partial or complete occlusion of the arterial lumen. "Collectively, overexpression of FAM110D and PLVAP in HAECs specifically impacts GRN195 gene activity along with several atherosclerosis-relevant EC phenotypes including chromatin condensation, adhesion, mitochondrial activity and proliferation." (PMID 40211055, 2025).
cerebral edema (1 paper, 2018). "In the present review, we discuss the history of the identification of PLVAP, focus on the current understanding of PLVAP as regulator of vascular permeability, and explore its potential as novel target for vasogenic cerebral edema and DME." (PMID 30231925, 2018).
colorectal cancer (1 paper, 2025). A primary or metastatic malignant neoplasm that affects the colon or rectum. "We showed that Plasmalemma Vesicle Associated Protein-1 (PV-1) serves as a marker of increased blood vessel permeability and is an independent predictor of colorectal cancer dissemination." (PMID 40691302, 2025).
fibrosis (1 paper, 2022). the formation of excess fibrous connective tissue in an organ or tissue in a reparative or reactive process. "A different study on CCl4-induced mouse fibrosis model identified plasmalemma vesicle-associated protein (PLVAP) as a protein highly expressed in mouse and human HSCs." (PMID 39872749, 2022).
liver steatosis (1 paper, 2022). "Capillarization then leads to liver steatosis, as shown in mice deficient in plasmalemma vesicle-associated protein (PLVAP), an endothelial-specific integral membrane glycoprotein that has been identified to be a component of endothelial fenestrae." (PMID 36010588, 2022).
lung adenocarcinoma (1 paper, 2025). A carcinoma that arises from the lung and is characterized by the presence of malignant glandular epithelial cells. "Tip cell proportions were elevated in early‐stage lung adenocarcinoma (LUAD) tissues and KT mice, with evidence suggesting they arise from capillaries type I. PLVAP expression was enriched in tumour endothelial cells, induced by TGFβ1, and negatively correlated with patient prognosis." (PMID 41431249, 2025).
lung carcinoma (1 paper, 2023). "In early-stage lung cancer nodules and metastatic lung cancer, IGFBP7+PLVAP+ tumor ECs were greatly amplified, whereas the proportion of extra-alveolar capillary ECs (cECs), EDN1+CCL2+ ECs, decreased." (PMID 37187731, 2023). "Moreover, during the progression of lung cancer, the proportion of EDN1+CCL2+cECs decreases, while the proportion of IGFBP7+PLVAP+ECs significantly increases." (PMID 37187731, 2023). "Similarly, another study also identified two types of tumor ECs: INSR+ tumor EC (INSRhiHSPG2+PLVAP+) and ACKR1+ tumor EC (ACKR1+SELP+IL1R1+) in early-stage lung cancer that radiologically manifests as part-solid nodules." (PMID 37187731, 2023).
medulloblastoma (1 paper, 2019). A malignant, invasive embryonal neoplasm arising from the cerebellum. "In mouse models of WNT-medulloblastoma, the intra-tumor capillaries resemble CVO capillaries in their high density, tortuosity, and GLUT1-/PLVAP+ phenotype." (PMID 30932813, 2019).
meningioma (1 paper, 2025). A generally slow growing tumor attached to the dura mater. "Therefore, we may speculate that targeting PLVAP therapy is expected to be a potential therapeutic molecule to inhibit the development of meningioma." (PMID 40496867, 2025).
osteoporosis (1 paper, 2019). A condition of reduced bone mass, with decreased cortical thickness and a decrease in the number and size of the trabeculae of cancellous bone (but normal chemical composition), resulting in increased fracture incidence. "Excluding genes without known specific functions (CDC27 and TNRC18), ARID2, HEBP1, LTBP1, and PLVAP were the only significant differences in the cancer group revealed by the gene-score methodology, while DFFA, FAM193A, and VEGFA were the only significant differences in the osteoporosis group." (PMID 31747953, 2019).
retinopathy of prematurity (1 paper, 2025). A bilateral retinopathy characterized by neovascularization, scarring, retinal detachment, and eventually blindness. "PLVAP is believed to plays a significant role in regulating vascular permeability and be linked to compromised barrier function in several retinal disorders in various retinal diseases, such as wet AMD, DR and retinopathy of prematurity (ROP)." (PMID 40308764, 2025).
Sepsis (1 paper, 2025). Sepsis is defined as life-threatening organ dysfunction caused by a dysregulated host response to infection. "Key genes like TNFSF10, TMCC2, and PLVAP genes show strong diagnostic potential, providing novel insights into sepsis pathogenesis and offering promising targets for future therapeutic interventions." (PMID 40362669, 2025). "Notably, TNFSF10, GUCD1, and PLVAP show strong associations with pathways sepsis-relevant sepsis development." (PMID 40362669, 2025). "Although the present study is limited by the lack of experimental validation, future work will incorporate qPCR, Western blotting, and functional assays to confirm the expression and biological roles of TNFSF10, TMCC2, and PLVAP in sepsis." (PMID 40362669, 2025). "In conclusion, our integrative approach identified several robust gene signatures, including TNFSF10, PLVAP, and TMCC2, as potential biomarkers of sepsis severity." (PMID 40362669, 2025). "Receiver operating characteristic (ROC) analysis demonstrated high predictive accuracy for sepsis progression, with AUC values of 0.973 (TMCC2), 0.969 (TNFSF10), and 0.897 (PLVAP)." (PMID 40362669, 2025). "The correlation matrix highlights strong positive relationships among key genes such as TNFSF10, EPB41, PLVAP, and TMCC2, suggesting their coordinated involvement in sepsis pathogenesis." (PMID 40362669, 2025).
Tinnitus (1 paper, 2023). Tinnitus is an auditory perception that can be described as the experience of sound, in the ear or in the head, in the absence of external acoustic stimulation. "The genes that were down-regulated in the tinnitus group, were influenced by more than just an outlier value, and had corresponding FC values of >1 included GFAP (logFC= −3.04), APLNR (−2.95), PREX2 (−1.44), and PLVAP (−1.04; all p < 0.01)." (PMID 37048724, 2023). "All genes except PLVAP were detected with real-time RT-qPCR in both groups (tinnitus and no tinnitus)." (PMID 37048724, 2023).
ulcerative colitis (1 paper, 2023). An inflammatory bowel disease involving the mucosal surface of the large intestine and rectum. "VEGF can stimulate in vitro expression of the PLVAP gene, and PV-1 is increased in patients with ulcerative colitis." (PMID 36674986, 2023).
Wilms tumor (1 paper, 2022). An embryonal neoplasm characterized by the presence of epithelial, mesenchymal, and blastema components. "PLVAP is expressed in fenestrated cells, e.g., in the liver endothelium or glomeruli of Wilms` tumor." (PMID 35633941, 2022).
tumor (58 papers, 2008 to 2026). "Beyond LUAD, PLVAP has been implicated in multiple tumour types via distinct upstream regulators and downstream pathways." (PMID 41431249, 2025). "In tumours, high PLVAP levels are linked to abnormal vasculature that restricts effector immune cell infiltration and supports immune evasion." (PMID 41431249, 2025). "Plasmalemma vesicle-associated protein (PLVAP)+ ECs are enriched in tumor tissues and are identified as HCC-specific." (PMID 39085965, 2024). "The recombinant monoclonal anti-PLVAP antibody caused tumor vascular thrombosis and necrosis of HCC in a xenograft model." (PMID 36033326, 2022). "Tumor angiogenesis in particular has been associated with increased levels of plasmalemma vesicle-associated protein (PLVAP), being typically induced in ECs of large, well-vascularized tumors." (PMID 33671551, 2021). "Especially, two tumor-specific cells, including EC-immature and EC-Tip cells were identified; both highly expressed plasmalemma vesicle-associated proteins (PLVAP) indicative of the presence of endothelial fenestrations and were enriched in similar biological pathways." (PMID 37336873, 2023). "Moreover, Spearman association analyses indicated that PLVAP was positively correlated with immunosuppressive subsets such as tumor-associated macrophages (TAMs), myeloid-derived suppressor cells (MDSCs), and regulatory T lymphocytes (Tregs) among those two datasets." (PMID 36033326, 2022). "Among these, GPC3 and PLVAP were consistently upregulated, implicating their roles in tumor progression and angiogenesis across ethnicities." (PMID 41216224, 2025). "We aimed to uncover the pro‐invasive role of PLVAP+ tip‐like ECs in the early progression of LUAD and to propose the TGFβ1‒PLVAP axis as a critical mechanism underlying early tumour–endothelium crosstalk." (PMID 41431249, 2025). "Tumour‐secreted TGFβ1 upregulated PLVAP in endothelial cells, promoting angiogenesis and tumour invasion." (PMID 41431249, 2025). "This supports a reinforcing feedback mechanism was involved PLVAP and TGFβ1, as well as functional divergence between tumour‐ and tip‐cell‐derived TGFβ1." (PMID 41431249, 2025). "Subsequently, we used shRNA to elevate PLVAP on HUVEC to simulate the elevated expression of PLVAP in ECs stimulated by tumour cells, and found that the tube‐forming ability of HUVEC was significantly enhanced after elevation of PLVAP." (PMID 41431249, 2025). "PLVAP expression is significantly upregulated in ECs of tumour tissues from various organs, including the liver, lung, kidney, pancreas, stomach, colon, small intestine, breast, brain, ovary, uterus, prostate, skin and lymph nodes." (PMID 41431249, 2025). "A further cluster of immature endothelial cells (Endo Imm), defined by expression of PLVAP, VWA1, and CA4, was identified and has been implicated in poor tumor prognosis." (PMID 40161579, 2025). "We found significantly enhanced PLVAP expression on ECs using human (A549) or mouse LUAD tumour cell lines (LKR Tgfbr2 KO) co‐cultured with HUVEC." (PMID 41431249, 2025). "Then, we co‐cultured HUVEC with A549 and found that HUVEC‐expressed PLVAP was able to regulate tumour cell invasion and migration." (PMID 41431249, 2025). "Functionally, PLVAP promoted endothelial cell invasion, migration and angiogenesis, and regulated tumour cell invasiveness." (PMID 41431249, 2025). "CD31 and PLVAP are both known to be widely expressed on tumour endothelial cells in HCC tumours tissues and are likely to play an important role in monocyte recruitment to the TME." (PMID 39684877, 2024). "Plasmalemma vesicle-associated protein (PLVAP)-positive endothelial cells have been identified in fetal, cirrhotic liver, and HCC, and are enriched in the tumor periphery." (PMID 36938978, 2023). "The expression of PLVAP induced by tumor cells increases the permeability of vessels by accelerating transcytosis of endotheliocytes through the founding trans-endothelial channel, fenestra, and diaphragm of the caveola." (PMID 36033326, 2022).
tumor (continued). "PLVAP was expressed in both endothelial cells and tumor cells, and expression in each cell type was scored separately." (PMID 35723333, 2022). "Compared to primary tumors, PLVAP expression was significantly higher in the tumor cells of all relapse samples (p = 0.02, n = 157)." (PMID 35723333, 2022). "Tumor ECs in early-stage tumors strongly expressed PLVAP, GSN, and TSC22D1, which are relevant to the development and cell-fate commitment of ECs15." (PMID 34764257, 2021). "In accordance with increased permeability of GBM vasculature, we observed a higher level of expression of PLVAP in ECs in the tumor core compared with ECs in peripheral tissue." (PMID 34228647, 2021). "C0 corresponded to tumor-associated [heparan sulfate proteoglycan 2 (HPSG2) and plasmalemmal vesicle-associated protein (PLVAP)] and C1 ECs were blood ECs (FLT)." (PMID 34900703, 2021). "In our study, the number of mice used in each experiment was limited, because infusion of anti-PLVAP Fab-TF into hair size tumor feeding femoral artery is technically challenging and has precluded us from having a larger number of mice in each experiement." (PMID 25376302, 2014). "The results indicated that PLVAP gene expression in HCC tissue was restricted to tumor vascular endothelial cells." (PMID 25376302, 2014). "The specific expression of PLVAP by tumor vascular endothelial cells was further confirmed by immunohistochemical staining using monoclonal anti-human PLVAP antibodies." (PMID 25376302, 2014). "Infusion of recombinant monoclonal anti-PLVAP Fab-TF into the main tumor feeding artery induced tumor vascular thrombosis and extensive tumor necrosis at doses between 2.5 μg and 12 μg." (PMID 25376302, 2014). "Further, we found that the upregulated PLVAP gene in TECs could regulate the invasion and migration of ECs, enhance angiogenesis, which in turn supports tumour cell invasiveness and movement, thus promoting tumour progression." (PMID 41431249, 2025). "We explored the factors that promote the transformation from capillaries type I to tip cell during tumour progression by differential gene analysis, and found that PLVAP was upregulated in tip cells in both human and mice, and negatively linked to survival rates among patients diagnosed with LUAD." (PMID 41431249, 2025). "However, studies on the function of PLVAP in early tumour progression are still very limited, especially in human early‐stage LUAD, which is rarely reported." (PMID 41431249, 2025). "This may explain that during tumour progression tumour cells promote tumour growth and metastasis by secreting TGFβ1 and activating neighboring ECs to express PLVAP." (PMID 41431249, 2025). "PLVAP may also participate in tumour immune regulation by modulating vascular permeability and endothelial barrier function." (PMID 41431249, 2025). "Furthermore, HCC LSECs express plasmalemma vesicle-associated protein (PLVAP), making them less permeable and potentially limiting the entry of lymphocytes and tumour-derived antigens." (PMID 37389120, 2023). "A follow-up study by the same group, furthermore observed that tumor-associated endothelial vessels contain specialized endothelial cells, high in CD276 and PLVAP as biomarkers, that are the main drivers for transporting NPs from the bloodstream into the tumor microenvironment." (PMID 36135572, 2022). "We reasoned that infusion of anti-PLVAP Fab-TF into the tumor feeding artery would provide a saturating concentration of anti-PLVAP Fab for binding to the target antigen and reduce the amount of Fab-TF required to achieve therapeutic effect through systemic administration." (PMID 25376302, 2014). "PLVAP expression is upregulated in tumor endothelium by VEGF." (PMID 24058663, 2013). "Notably, the VEGF-VEGFR-activated pathway network in the endothelium included the venous EC-specific proangiogenic gene PLVAP, suggesting that the angiogenesis-promoting transcriptomic changes observed in the ECs may be initiated by the tumor cells." (PMID 39803458, 2025).